EEF1A2 (eukaryotic translation elongation factor 1 alpha 2)
Diseases named in the same sentence as EEF1A2 in open-access papers (continued):
Sharing a sentence is not in itself a finding about the gene and the disease.
cancer (continued). "The present study identified that the expression of EEF1A2 increased in LUAD compared to para-carcinoma tissues and was similarly higher in metastatic tissues compared to primary tumour tissues." (PMID 33473168, 2021). "It is reported that eEF1A2 is an important protein involved in protein translation elongation, and eEF1A2 was identified as a putative oncogene in many human cancers (breast, ovary, liver, pancreas, lung, and prostate)." (PMID 31876369, 2020). "Additional caution has to be taken when analyzing samples from cancer patients, as eEF1A2 can be overexpressed in such cases." (PMID 30864069, 2019). "While some pro-oncogenic perturbations like upregulation of metalloproteinases governed by eEF1A2 or reduction of oxidative stress have been described, the exact mechanism of action as a bone fide cancer gene remains to be identified." (PMID 30306263, 2018). "Using plitidepsin to release eEF1A2 from those protein complexes, their effects on cancer cell survival were analysed in vitro." (PMID 30420615, 2018). "We found that there is a reciprocal relationship between EEF1A1 and EEF1A2 transcript levels in tumor tissues of different cancer types, indicating towards a tight regulation of any one isoform over another, in cancers also." (PMID 29342219, 2018). "Through its binding to PKR, eEF1A2 provides a survival boost to cancer cells, constituting an Achilles heel that can be exploited in anticancer therapy." (PMID 30420615, 2018). "Through several not-fully-characterised moonlighting functions, translation elongation factor eEF1A2 is known to provide a fitness boost to cancer cells." (PMID 30420615, 2018). "We have previously shown that eEF1A2 is the target of plitidepsin, a marine drug currently in development for cancer treatment." (PMID 30420615, 2018). "Taken together, these results show that the fitness boost that the moonlighting functions of eEF1A2 provide to cancer cells constitutes an Achilles heel that can be purposely exploited in anticancer therapy." (PMID 30420615, 2018). "In cancer cells, aberrant eEF1A2 expression would provide resistance to cell death, an essential advantage that would help tumour cells to overcome their intrinsic weaknesses, allowing them to grow." (PMID 30420615, 2018). "Overall, we see that in addition to EEF1A2; EEF1G, EEF1D, EEF1E1 and EEF2 are significantly upregulated in different cancer types and are associated with better and worse survival outcome in specific cancers." (PMID 29342219, 2018). "Our data stress the important role of the “moonlighting” effects of eEF1A2 in the maintenance of cancer phenotype." (PMID 30420615, 2018). "These preliminary studies suggest that in addition to EEF1A2, other translation elongation factors are involved in multiple human cancers." (PMID 29342219, 2018). "EEF1A2 is an eukaryotic elongation factor of which its expression downregulates through interaction with protein p16 (INK4a) leading to inhibition of cancer cell growth." (PMID 26892682, 2016). "Studying cancer cell lines derived from breast, lung, prostate, and skin, eEF1A2 gene expression exhibited the highest alteration in the cancer cell lines compared to normal controls using a profiling array." (PMID 25905039, 2015). "The ZNF217 gene belongs to the 20q13 region, a region frequently amplified in human cancers and importantly, ZNF217 protein interferes and cooperates with proteins encoded by other genes present in this region (AURKA, BCL2L1, eEF1A2)." (PMID 26431164, 2015). "On the contrary, compared with PZHPV-7, a significant and remarkable rise of EEF1A2 mRNA levels was found in all three cancer cell lines with the highest level found in the LNCaP (P<0.0001)." (PMID 22095224, 2012). "This is perhaps best exemplified by the roles identified for the protein elongation factor, EEF1A2, in a number of human cancers." (PMID 20505761, 2010).
cancer (continued). "It has been very difficult, however, to relate genetic features of these cancers with levels of EEF1A2 protein expression." (PMID 20505761, 2010). "The data obtained are an essential step in the move towards an understanding of the functional divergence of the near-identical eEF1A1 and eEF1A2 isoforms, and in particular, the cancer-related properties of the latter." (PMID 18221514, 2008). "First, their differential expression patterns, with eEF1A1 being ubiquitously expressed and eEF1A2 restricted to neurons, muscle, and more frequently overexpressed in cancers, suggest that isoform-specific inhibitors could achieve better therapeutic windows." (PMID 40806463, 2025). "Strategies targeting EEF1A2 function hold promise as a therapeutic approach in cancer treatment." (PMID 39083441, 2025). "These research findings strongly indicate that EEF1A2 plays a crucial role in promoting tumor cell survival by preventing apoptosis, as evidenced in multiple cancer types, and its binding to Prdx-I contributes to resistance against oxidative stress-induced cell death." (PMID 38172654, 2024). "Furthermore, the specific upregulation of EEF1A2 in cancers renders it an appealing target for drug development." (PMID 38172654, 2024). "Overall, EEF1A2 plays a crucial role in mediating oncogenic effects in various cancer types, operating through the activation of multiple signaling pathways, including PI3K–AKT, JAK/STAT, and ERK, which promote tumor cell migration, invasion, and proliferation." (PMID 38172654, 2024). "We have discussed the multiple facets of regulation mediated by EEF1A2 in cancer progression." (PMID 38172654, 2024). "The rationale behind the divergent influence of EEF1A2 on prognosis across various cancer types may potentially stem from its distinct roles within differing tissue contexts or different molecular subtypes." (PMID 38172654, 2024). "In addition to its role in aminoacyl‐tRNA delivery to the ribosome, EEF1A2 is known for its pro‐oncogenic activity in many tumors, enhancing cancer cell proliferation and inhibiting apoptosis." (PMID 37819151, 2023). "DDX5 and eEF1A2 are two oncogenes in several cancer types according to previous researches 25-27." (PMID 33859743, 2021). "Compared to the para-carcinoma tissues, tumour tissues exhibited strong expression of EEF1A2." (PMID 33473168, 2021). "Although no RNA-seq data are available for Eso-AdenoCA samples, SCNA analysis indicated that EEF1A2 is amplified in 69.5% (66/95) of Eso-AdenoCA samples (vs. 27.9% of non-Eso-AdenoCA samples), suggesting a potential gain-of-function role in this cancer type." (PMID 32024818, 2020). "Several studies demonstrated that eEF1A2 acts as a growth-enhancing protein in many human cancers." (PMID 31220107, 2019). "Our evidence suggests that in TNBC high levels of eEF1A2 protein sustain cancer aggressiveness." (PMID 31220107, 2019). "In the recent years, a translation elongation factor of the eukaryotic elongation factor 1 alpha (EEF1A) family, namely eukaryotic elongation factor 1 alpha 2 (EEF1A2) has attracted much attention due to multiple studies highlighting its role as an oncogene, across different cancers." (PMID 29342219, 2018). "However, apart from EEF1A2, the prognostic significance of other translation elongation factors remain largely unexplored across different cancer types." (PMID 29342219, 2018). "This new eEF1A2–PKR complex has been proven essential for the survival of cancer cells." (PMID 30420615, 2018). "The compound exerts a novel mechanism of action by targeting isoform 2 of the translation elongation factor eEF1A (eEF1A2), which is a putative oncogene that has been shown to be upregulated in pancreatic and other cancers with expression levels that are inversely correlated with clinical outcome." (PMID 30306263, 2018).
cancer (continued). "It is quite possible that like EEF1A2, other translation factors discussed herein could also be promising therapeutic targets and prognostic biomarkers in human cancers as most of them are seen to overexpressed in a wide variety of cancers." (PMID 29342219, 2018). "Besides, other cancer-related factors were also found to be direct targets of miR-663, such as EEF1A2 and HSPG2." (PMID 27667893, 2016). "Interestingly, and in line with a role for eEF1A2 as an oncogene, the upregulation of lysosome biogenesis has been reported to be important for the support of cancer cell metabolic requirements." (PMID 27807005, 2016). "Our data indicate that plitidepsin targets eEF1A2 in cancer cells." (PMID 27713531, 2016). "Notably, compared with PZHPV-7, in all cancer cells, eEF1A2 protein was significantly increased in both cytoplasmic and cytoskeletal/nuclear fractions." (PMID 22095224, 2012). "Additionally, genes such as EEF1A2 (protein synthesis and cancer cell survival), RAMP2 (cardiovascular homeostasis), PLAGL1 (cell growth suppression and differentiation activation), and STRIP2 (stem cell differentiation and cell morphology regulation) were also suppressed." (PMID 40427555, 2025). "EEF1A2 targeting therapies could hold promise in a wide variety of cancer types." (PMID 38172654, 2024). "Consequently, the specific role of EEF1A2 in cancers derived from glucagon-producing pancreatic islet cells remains unclear." (PMID 38172654, 2024). "Collectively, the evidence presented strongly supports the conclusion that EEF1A2 plays a crucial role in promoting migratory and invasive characteristics of tumor cells through various signaling cascades, suggesting it as a potential target for therapeutic interventions in multiple cancer types." (PMID 38172654, 2024). "From a more speculative perspective, this will also show whether the antiproliferative effect of this cyclic depsipeptide is only driven by its interaction with eEF1A2 or whether there are other indirect events that ultimately trigger apoptosis in cancer cells." (PMID 27713531, 2016). "Importantly, the appearance of eEF1A2 in tissues in which the variant is not normally expressed can be coupled to cancer development, as shown for ovary and suggested in some cases of breast cancer." (PMID 18221514, 2008). "Importantly, the appearance of eEF1A2 in tissues in which the variant is not normally expressed can be coupled to cancer development." (PMID 18221514, 2008). "However, given both that exon 1 is noncoding, and that this tumour shows expression of eEF1A2 at the RNA but not the protein level, the mutation is unlikely to be of functional significance in terms of cancer." (PMID 17437010, 2007). "Whereas lack of eEF1A2 gives rise to the wasted mouse phenotype, which involves motor neuron degeneration, inappropriate overexpression has now been linked to cancer." (PMID 17437010, 2007). "The canonical function carried out by EEF1A2 in cells is redundant with the activities of the other EEF1A isoform, EEF1A1, which is also a promising candidate for targeting cancers." (PMID 38172654, 2024). "EEF1A1, EEF1A2 and EEF1D have previously been reported to be potential candidates for gene amplification, leading to observed overexpression in certain cancers." (PMID 29342219, 2018). "Higher expression of EEF1A2, EEF1B2, EEF1G, EEF1D, EEF1E1 and EEF2 was observed in most of the cancer types, whereas reverse trend was observed for EEF1A1." (PMID 29342219, 2018). "The 20q13.33 region overlapped with several cancer related genes such as CDH4, LAMA5, RPS21, KIAA1510, TNFRSF6B (M68, DcR3), RTEL, EEF1A2 and PTK6." (PMID 24165089, 2013). "As was the case in other cancers, not many studies are available about the effect of EEF1A2 on the survival of cancer patients." (PMID 38172654, 2024).
cancer (continued). "Interaction with EEF1A2 could modulate the activity of ST6GALNAC1/ST6GALNAC2 and sialoglycan synthesis differently in normal and malignant tumour tissues." (PMID 39348343, 2024). "Up until now, studies have predominantly focused on cancers derived from pancreatic ductal epithelium cells, and there have been no reports on EEF1A2 in cancers originating from glucagon-producing pancreatic islet cells." (PMID 38172654, 2024). "The significantly overexpressed sEV proteins in the BC plasma-derived UCT isolates were ALB, COL1A1, CSN1S1, EEF1A2, and RPL3; and the C1S, C5, C7, and CFHR2 sEV proteins in the UCT isolates were the most downregulated proteins in the BC plasma compared to the non-cancer control." (PMID 37895140, 2023). "Keeping these lacunae in hindsight, we have undertaken a pan-cancer approach for comprehensive analysis of expression levels of seven elongation factors namely, EEF1A1, EEF1A2, EEF1B2, EEF1G, EEF1D, EEF1E1 and EEF2, using publicly available databases (Oncomine and TCGA)." (PMID 29342219, 2018). "In addition to EEF1A2, other translation factors EEF1B2, EEF1G, EEF1D, EEF1E1, and EEF2 were also found to be frequently overexpressed in different cancers." (PMID 29342219, 2018). "The fitness boost that these eEF1A2 non-canonical functions provide to cancer cells would then be important for their growth and survival." (PMID 30420615, 2018). "However, all eight of those cancers not expressing eEF1A2 also had copy numbers significantly exceeding that found in normal diploid blood DNA." (PMID 17437010, 2007). "In contrast to eEF1A2, the cytoplasmic eEF1A1 did not significantly differ between non-tumourigenic and tumourigenic cells and an increase of the protein was seen only in the cytoskeletal/nuclear fraction but without significant variation between the cancer cell lines tested." (PMID 22095224, 2012). "Curiously, in the non-tumourigenic PZHPV-7, amplification of EEF1A1 and EEF1A2 genes was detected, even though these cells that barely express EEF1A2 and EEF1A1 expression did not result to be higher than in cancer cells." (PMID 22095224, 2012).
tumor (160 papers, 1994 to 2025). "This decrease correlates with reduced levels of TGFβRI and TGFβRII receptors and alterations in SMAD3 and its phosphorylated variant, pSMAD3, further illustrating the contribution of EEF1A2 to increasing tumor aggressiveness." (PMID 39083441, 2025). "In summary, KAT8 enhances the translation of tumour‐associated proteins by mediating eEF1A2‐K408la, ultimately leading to tumour progression." (PMID 40984037, 2025). "EEF1A2, involved in protein synthesis, is associated with increased tumor aggressiveness when overexpressed." (PMID 39083441, 2025). "EEF1A2 expression is associated with lung adenocarcinoma metastasis, poor prognosis, tumor grade, disease stage, and short survival of suffering patients." (PMID 39083441, 2025). "The precise molecular mechanism by which stroma supports high protein synthesis in the tumor remaining enigmatic, we here show that stromal syntenin deficiency induces a fivefold increase in the elongation factor EEF1A2 in AML." (PMID 37819151, 2023). "More work is needed to ascertain the precise function(s) of eEF1A2 that is/are impaired by plitidepsin to cause tumor cell death so efficiently." (PMID 27713531, 2016). "Firstly, we summarized eEF1A2 expression by means of the semi-quantitative H score and, after the adjustment for tumor stage, a statistically significant association between increasing values of the biomarker and the increase of hazards for adverse events was observed (recurrence-DFS or death-BCSS)." (PMID 31220107, 2019). "E7 protein of HPV38 has been shown to interact with both eEF1A1 and eEF1A2 proteins leading to cellular immortalization and transformation of primary keratinocytes probably through disruption of actin stress fiber formation, a critical event linked to tumor formation." (PMID 25905039, 2015). "In two GBC cell lines, eEF1A2 knockdown impaired cell proliferation, migration, and invasion in vitro and inhibited tumor growth and lymph node metastasis in vivo, whereas overexpression of eEF1A2 promoted these processes." (PMID 41705259, 2025). "Mechanistically, trimethylation at the K36 site of eEF1A2 increased the GTPase activity of eEF1A2 and enhanced tumor promoting signals including ERK1/2 and AKT by promoting the ribosome total protein synthesis." (PMID 41705259, 2025). "eEF1A2‐K408la promotes mRNA translation and protein synthesis, ultimately exacerbating tumour cell proliferation." (PMID 40984037, 2025). "Several reports utilizing shRNA or siRNA-based targeting of EEF1A2 levels in cancerous cell lines have shown how depletion of EEF1A2 compromises the oncogenic potential of tumor cells." (PMID 38172654, 2024). "Over the past decade, a substantial body of evidence has been amassed, strongly indicating that EEF1A2 plays a crucial role in promoting the migratory and invasive characteristics of tumor cells." (PMID 38172654, 2024). "EEF1A2 knockdown in HCC cell lines in yet another study led to the abrogation of cancerous attributes of the tumor cells via the reduction of PI3K/AKT/NF-kB signaling." (PMID 38172654, 2024). "A subsequent study with a higher sample size (30 pairs of PCa tissues) reported that most of the tumor tissues had elevated EEF1A2 transcripts and protein levels compared with corresponding normal tissue." (PMID 38172654, 2024). "Aplidin is a first-in-class cyclic depsipeptideplitidepsin isolated from marine tunicate named Aplidium albicans, and it interacts strongly with eukaryotic elongation factor 1A2 (eEF1A2) in the cells of a tumor." (PMID 35268639, 2022). "The eEF1A1 and eEF1A2 proteins have been suggested as possible features of cell transformation and tumour progression." (PMID 35456960, 2022).